S100A1 (S100 calcium binding protein A1)
Description:
Small calcium binding protein that plays important roles in several biological processes such as Ca(2+) homeostasis, chondrocyte biology and cardiomyocyte regulation. In response to an increase in intracellular Ca(2+) levels, binds calcium which triggers conformational changes. These changes allow interactions with specific target proteins and modulate their activity. Regulates a network in cardiomyocytes controlling sarcoplasmic reticulum Ca(2+) cycling and mitochondrial function through interaction with the ryanodine receptors RYR1 and RYR2, sarcoplasmic reticulum Ca(2+)-ATPase/ATP2A2 and mitochondrial F1-ATPase. Facilitates diastolic Ca(2+) dissociation and myofilament mechanics in order to improve relaxation during diastole.
Synonyms: S100A; S100-alpha; S100
Tractability: Small molecule: a structure with a bound ligand is known. Antibody: its Gene Ontology location is reachable by antibodies, with high confidence.
Gene: Protein-coding gene on chromosome 1 (153,627,926 to 153,632,044, forward strand). Ensembl gene ENSG00000160678.
Subcellular location: Cytoplasm; Sarcoplasmic reticulum; Mitochondrion
Subcellular location (Human Protein Atlas): Cytosol; Golgi apparatus; Nucleoplasm
Pathways (Reactome):
Immune System: ER-Phagosome pathway; MyD88:MAL(TIRAP) cascade initiated on plasma membrane; Regulation of TLR by endogenous ligand
Disease: IRAK4 deficiency (TLR2/4); MyD88 deficiency (TLR2/4)
Gene Ontology:
Molecular function: ATPase binding; identical protein binding; protein binding; protein homodimerization activity; S100 protein binding; calcium ion binding; calcium-dependent protein binding
Biological process: positive regulation of sprouting angiogenesis; substantia nigra development; vasodilation; intracellular signal transduction; regulation of heart contraction
Cellular component: cytoplasm; cytosol; nucleus; sarcoplasmic reticulum; extracellular region; mitochondrion; protein-containing complex
Genetic constraint (gnomAD): Loss-of-function variants: 3 observed, 8.05 expected, observed/expected ratio (o/e) 0.37, 90% interval 0.17 to 0.96. That is too few expected variants to judge how well the gene tolerates losing a copy. Missense variants: 126 observed, 121.66 expected, observed/expected ratio (o/e) 1.04, 90% interval 0.89 to 1.2. Synonymous variants: 49 observed, 51.82 expected, observed/expected ratio (o/e) 0.95, 90% interval 0.75 to 1.2.
Homologues: Orthologues: chimpanzee S100A1 (100% identical), guinea pig S100A1 (99% identical), pig S100A1 (99% identical), dog S100A1 (98% identical), rabbit S100A1 (98% identical), mouse S100a1 (94% identical), rat S100a1 (94% identical), macaque S100A1 (77% identical), zebrafish s100a1 (71% identical), tropical clawed frog s100a1 (64% identical). Paralogues in human: S100Z (57% identical), S100B (56% identical), S100P (52% identical), S100A2 (50% identical), S100A4 (49% identical), S100A10 (46% identical), S100A5 (45% identical), S100A6 (43% identical), S100A3 (41% identical), S100A11 (40% identical), S100A12 (37% identical), S100A13 (36% identical), and 9 more.
Diseases named in the same sentence as S100A1 in open-access papers:
S100A1 is named in the same sentence as 144 diseases in open-access papers, as found by Europe PMC text mining. Sharing a sentence is not in itself a finding about the gene and the disease. The quoted sentences say what the papers report.
melanoma (30 papers, 2015 to 2025). A malignant, usually aggressive tumor composed of atypical, neoplastic melanocytes. "High expression of S100A1 was apparent, pointing to a unique and strong association between this melanoma marker and the Mit subtype." (PMID 40075679, 2025). "However, S100A1 overexpression is also associated with other diseases, including breast cancer, cardiovascular diseases, and ovarian cancer, which limits its specificity for melanoma diagnosis." (PMID 40313257, 2025). "To further elucidate the interactive network of tumor-intrinsic S100A1, M1-like macrophage polarization, and T-cell function, we modified B16 melanoma cells to express the ovalbumin-derived CD8+ T-cell epitope OVA257-264 (SIINFEKL)." (PMID 40090947, 2025). "The custom-designed 10× Xenium gene panel contained 30 human genes, including pathologically established BCR and S100A1 melanoma markers and RPL23 and RPL35A as the most representative members of the melanoma CTC signature." (PMID 39831781, 2025). "Tumor cells from both modalities were highly similar, and key melanoma marker genes—including S100A1, MLANA, MCAM, and PRAME—were consistently highly expressed." (PMID 41446065, 2025). "Here, a two‐step strategy for on‐site diagnosis of MM is developed based on the extraction and direct visual quantification of S100A1, a biomarker for melanoma." (PMID 38417122, 2024). "For example, S-100A1, S-100A2, and S-100A4 are produced by melanocytes, and have been found to be elevated in some cases of melanoma." (PMID 37504268, 2023). "Studies have shown that S100A1 is overexpressed in various types of cancers, including breast cancer, melanoma, osteosarcoma and prostate cancer." (PMID 37538932, 2023). "In summary, the combination of NMR and computational approaches provided insight into how S100A1 versus S100B bind small molecules specifically, which will enable improved drug design efforts to inhibit elevated S100B in melanoma." (PMID 33450915, 2021). "However, despite its high sensitivity, this method is currently limited to detecting S100A1 alone, excluding other potential melanoma biomarkers, which restricts its broader applicability." (PMID 40313257, 2025). "Moreover, mRNA expression of the S100a1 melanoma marker had a 5.1‐fold increase (P < 0.05) in tumors of BPC‐Panx1−/− compared to the skin, indicating that the development of primary tumors occurred independently of Panx1 expression." (PMID 38327091, 2024). "Furthermore, the upregulation of S100A1 is found in tumors such as melanoma (> 100-fold increase), renal cell carcinoma and ovarian cancer." (PMID 34944467, 2021). "A recent study also suggested that S100A1 competes with S100A4 for binding to the V-domain of RAGE, suggesting that S100A1/RAGE interaction might influence cell proliferation in melanoma." (PMID 33256110, 2020). "In a different study, the immunohistochemical analysis of melanoma tissues showed a comparatively higher expression of S100A1 in melanoma than in benign melanocytic tumors, suggesting that S100A1 may play a critical role in melanoma progression." (PMID 33256110, 2020). "S100A1 interaction with TRPM-1 could therefore be an important component in melanoma progression." (PMID 33256110, 2020). "Studies have shown that serum S100A1 expression levels are significantly elevated in melanoma patients compared to non-melanoma individuals." (PMID 40313257, 2025). "It is important that S100B inhibitors designed to control malignant melanoma do not block S100A1, ensuring that normal skeletal and cardiac muscle function is retained." (PMID 33450915, 2021). "S100A1 is also highly expressed in melanoma tumors, but it differs from S100B in that it is not actively secreted in the serum." (PMID 33256110, 2020). "In their study, more than 90% of the malignant melanomas were found to express these proteins; S100A1 specifically was present in all types of melanomas but was not present in neurofibromas, schwannomas, or malignant peripheral nerve sheath tumors." (PMID 33339193, 2020).
melanoma (continued). "On these grounds, the use of the anti-S100-A1 antibody in our study may have failed to provide a complete picture on S100 upregulation in gray horse melanoma cells by IF." (PMID 38891088, 2024). "Indeed, S100A1 was not a prognostic factor in various solid tumors, including NSCLC, breast cancer and melanoma, implying its potential in predicting immunotherapy efficacy." (PMID 40090947, 2025).
breast carcinoma (20 papers, 2012 to 2025). "Studies have shown that S100A1 promotes the proliferation and invasion of breast cancer cells and is associated with a poor prognosis in breast cancer patients." (PMID 37538932, 2023). "In breast cancer, S100A1 has been found to be overexpressed in invasive ductal carcinomas, which are the most common type of breast cancer." (PMID 37538932, 2023). "This lncRNA through modulation of S100A1/Hippo and miR-363-5p/S100A1 pathways can participate in the pathogenesis of breast cancer and nasopharyngeal carcinoma, respectively." (PMID 35317077, 2022). "Huang and Xue suggested the upregulation of lncRNA FOXD2-AS1 in breast cancer cell lines and its positive relationship with S100A1 (Calcium-binding protein A1) gene expression." (PMID 36685962, 2022). "It was reported that lncRNA FOXD2-AS1/S100A1/Hippo axis was involved in tumourigenesis of breast cancer." (PMID 36685962, 2022). "It has been reported that S100A1 expression was significantly related with favorable OS in breast cancer patients, which is in accordance with all ovarian cancer patients, regardless of specific subtypes." (PMID 30558666, 2018). "Our results indicated that high mRNA expression of S100A8, S100A9, S100A11 and S100P were found to be significantly correlated to worse outcome, while S100A1 and S100A6 were associated with better prognosis in all breast cancer patients." (PMID 28051137, 2017). "utilized scRNA-seq technology to identify three functionally heterogeneous subpopulations of TANs in breast cancer: Neutrophil_IFIT1, Neutrophil_DUSP6, and Neutrophil_S100A1.The IFIT1+ subpopulation exhibits high expression of ISG15, MX1, and IFIT1, demonstrating antigen-presenting capabilities." (PMID 40568594, 2025). "Nevertheless, some S100 family members, for example S100A1, S100A13 or S100G have been rarely studied in breast cancer." (PMID 28051137, 2017). "The S100A1+subpopulation promotes a pro-inflammatory microenvironment and accelerates angiogenesis and matrix remodeling by releasing leukotriene B4(LTB4), ROS, and matrix metalloproteinase-9(MMP9), directly facilitating breast cancer metastasis." (PMID 40568594, 2025). "Although S100A1 does not seem to be directly involved in breast cancer signalling, it was shown that S100A1 reduces the activity of intracellular S100A4." (PMID 32722137, 2020).
heart failure (18 papers, 2012 to 2025). Inability of the heart to pump blood at an adequate rate to meet tissue metabolic requirements. "Circulating BNP and NT proBNP levels are normally very low, but they are significantly increased in patients with heart failure, while S100A1 expression levels are decreased and positively associated with heart failure severity, progression, and mortality." (PMID 37217870, 2023). "S100A1 protein may help to prevent arrhythmias caused by abnormal Ca2+ concentration and reduce the susceptibility of cardiomyocytes to arrhythmia in heart failure by regulating the function of RyR2." (PMID 37217870, 2023). "S100A1 expression is downregulated in heart failure with reduced ejection fraction (HFrEF) and right‐sided heart failure due to pulmonary hypertension, which contributes to progression and mortality in both diseases [S26–S28]." (PMID 40468979, 2025). "S100A1 overexpression has been shown to rescue cardiac function through enhanced Ca2+ handling and myofibrillar protein Ca2+ responsiveness in heart failure models." (PMID 41243395, 2025). "Through S100A1 gene targeting therapy, even a modest change in S100A1 protein can also prove in vitro treatment of human cardiac failure." (PMID 41195005, 2025). "S100A1 protein expression is downregulated in heart failure, especially in end-stage heart failure, and is increased in cardiac hypertrophy." (PMID 37217870, 2023). "Among the S100 family, S100A1 has the highest concentration in the myocardium, and its protein concentration level determines the likelihood of heart failure and contractile function following myocardial infarction." (PMID 34366855, 2021). "In the setting of heart failure (where S100A1 is down-regulated), its restoration via rAAV6-S100A1 in rats restored cardiac function and improve Ca2+ handling via a SERCA2a-dependent mechanism." (PMID 34076247, 2021). "Since S100A1 plays a crucial role in these processes, decreased S100A1 expression in cardiomyocytes has been well documented in heart failure 22-24." (PMID 31523180, 2019). "Variation in S100A1 expression have been reported in various diseases, including malignant tumor, heart failure, diabetes, ischemia, and chronic pulmonary hypertension." (PMID 30558666, 2018). "S100A1 plays an important role in heart failure, and S100A1 gene therapies were recently implemented in the human clinical trials." (PMID 29444082, 2018). "A variety of animal heart failure models provided further evidence for decreased cardiac S100A1 protein levels as a molecular signature of failing myocardium in vivo." (PMID 28427148, 2017). "Studies have shown that AAV9 enables broad myocardial distribution following intravenous or intracoronary injection and has demonstrated superior performance in delivering therapeutic genes such as SERCA2a, cBIN1, MYBPC3, and S100A1 in various models of heart failure and inherited cardiomyopathies." (PMID 41179895, 2025). "This might aid a deepened understanding of the molecular S100A1/RyR2 liaison given the therapeutic potential of S100A1 in heart failure." (PMID 38819384, 2024). "Advanced heart failure may change the expression of S100A1 in cardiomyocytes, resulting in lowering S100A1 tissue levels, and overexpression of S100A1 can effectively improve heart failure." (PMID 37217870, 2023). "Recent studies showed that S100A1 is likely related to the pathogenesis of heart failure." (PMID 37217870, 2023). "Moreover, adenoviral delivery of S100A1 was effective in the treatment of heart failure in small and large animals and improving the failing function of animal and human cardiomyocytes." (PMID 37217870, 2023). "S100A1 plays an important role in the occurrence and development of heart failure." (PMID 34366855, 2021). "For instance, because of the role of the ion as a key regulator of cardiac function, cardiomyopathies, and heart failure, S100A1-based gene therapy may be developed for clinical trials." (PMID 31936886, 2020).
heart failure (continued). "Importantly, the S100A1 protein is expressively downregulated in human end-stage heart failure, interpreting S100A1 and role of Ca2+ appropriate targets for cardiac gene therapy." (PMID 31936886, 2020). "Adeno-associated virus-mediated S100A1 gene transfer in failing cardiomyocytes was also shown to be able to restore the contractile function, suggesting a potential implication of AAV-mediated S100A1 gene therapy in heart failure." (PMID 29379499, 2017). "Moreover, adenoviral delivery of S100A1 was effective in the treatment of heart failure in small and large animals and improving the failing function of animal and human cardiomyocytes, clearly positions S100A1 as an appropriate target for cardiac gene therapy [S28, S29]." (PMID 40468979, 2025). "Likewise, S100A1 is up-regulated in a disease-specific manner, so developing S100A1-specific inhibitors may aid in treating diabetes, neurological diseases, heart failure, and other cancers." (PMID 33450915, 2021). "In addition, S100A1 knock-down alone could significantly aggravate heart failure in rats with permanent LAD-ligation (p < 0.05 vs. IHF group)." (PMID 34366855, 2021). "A study highlighted S100A1’s ability to restore calcium cycling in cardiomyocytes, improving contractility in heart failure models, and gene therapy using AAV-S100A1 showed reduced fibrosis and hypertrophy in rodents." (PMID 40492113, 2025). "Studies have shown that S100A1 protein levels in the heart tissue of patients with end-stage heart failure are reduced, and the lack of S100A1 accelerates heart failure in laboratory animals." (PMID 34366855, 2021).
ovarian carcinoma (10 papers, 2018 to 2025). A malignant neoplasm originating from the surface ovarian epithelium. "S100A1 is overexpressed in ovarian cancer tissues, and is associated with lymph node metastasis, FIGO stages, and tumor grades." (PMID 39742274, 2024). "For example, S100A1 serves as a favorable prognostic factor in endometrioid subtypes of ovarian carcinomas, whereas its expression is associated with poor prognosis in ovarian and endometrial endometrioid carcinomas." (PMID 35177036, 2022). "Furthermore, in vitro experiments have shown that S100A1 promotes the proliferation and migration of ovarian cancer cells." (PMID 39742274, 2024). "Similar findings were also observed in ovarian carcinoma cells, supporting observations that S100A1 plays an important role in tumor cell migration through interaction with different components of the cytoskeleton including microtubule and intermediate filaments." (PMID 35177036, 2022). "Thus, we suppose that S100A1 may play a more important role in disease relapse or progression in endometrioid subtypes of ovarian cancer patients." (PMID 30558666, 2018). "In particular, increased expression of S100A1, S100A4, S100A7, and S100A14 has been documented in multiple cancers including ovarian cancer." (PMID 31739800, 2019).